MEG3 (maternally expressed 3)
Diseases named in the same sentence as MEG3 in open-access papers (continued):
Sharing a sentence is not in itself a finding about the gene and the disease.
bladder cancer (44 papers, 2013 to 2025). "Therefore, activation of autophagy and an increase in cell proliferation is the underlying mechanism of aberrant MEG3 expression in bladder cancer." (PMID 24006935, 2013). "In vitro and in vivo assays have revealed that MEG3 inhibits the expression of miR-494 in bladder cancer cells." (PMID 40242248, 2025). "Overexpression of MEG3 inhibited the transcription of c-Myc in a c-Jun-dependent manner, thereby preventing bladder cancer invasion and metastasis." (PMID 40242248, 2025). "In bladder cancer cells treated with cisplatin, MEG3 overexpression induces cell apoptosis, downregulates the anti-apoptotic protein Bcl2, and upregulates the pro-apoptotic proteins cleaved-caspase-3 and Bax." (PMID 40242248, 2025). "Patients with bladder cancer have lower serum levels of MEG3 than healthy subjects and patients with benign disease." (PMID 40242248, 2025). "Their approach mirrors MEG3’s strategy of miRNA modulation but targets different specific miRNAs, enhancing the suppression of invasive behavior in bladder cancer." (PMID 40242248, 2025). "In human bladder cancer cell lines, activation of MEG3 inhibited autophagy, whereas inhibition of MEG3 induced autophagy." (PMID 40242248, 2025). "Additional research is required to fully elucidate the underlying mechanisms and investigate the therapeutic potential of MEG3 for the management of bladder cancer." (PMID 40242248, 2025). "MEG3 plays a vital role in the suppression of tumors in several forms of cancer, including bladder cancer." (PMID 40242248, 2025). "Overexpression of MEG3 increases the sensitivity of bladder cancer cells to the chemotherapeutic agent, cisplatin." (PMID 40242248, 2025). "In bladder cancer, MEG3 was found to function as a ceRNA for PTEN by competitively binding miR-494, thus repressing the proliferation, migration and invasion and promoting the apoptosis of tumour cells." (PMID 36831352, 2023). "Most studies have indicated that lincRNAs and snoRNAs are upregulated in bladder cancer and associated with oncogenesis, progression and metastasis, although GAS-5, MEG3 and linc00641 were shown to be tumour suppressor genes and were downregulated in BLCA." (PMID 36831352, 2023). "Consistent with our results, MEG3 has been previously reported to be a tumor suppressor in various types of cancers, including that of cervical, gastric and bladder cancers." (PMID 34140005, 2021). "Another study showed that lower expression of MEG3 was related to poor recurrence-free survival in bladder cancer." (PMID 32065781, 2020). "As recently reviewed, it has been found that lncRNA MEG3 significantly decreased in human invasive bladder cancers, and its exogenous expression can inhibit the invasiveness of human bladder cancer cells." (PMID 32249490, 2020). "A study on bladder cancer validated that by competing with PHLPP2 (PH domain and leucine-rich repeat protein phosphatase 2) mRNA to bind miR-27a, thereby promoting the expression of PHLPP2, MEG3 can restrain the invasion and metastasis of bladder cancer cells." (PMID 33520725, 2020). "Of these, XIST, H19, MALAT1, MEG3 play a role in tumor proliferation, suppression, and metastasis of bladder cancer." (PMID 31379598, 2019). "Our previous study showed that lncRNA Maternally Expressed Gene 3 (MEG3) is downregulated in bladder cancer and regulates cancer cell proliferation by inhibiting Wnt/β-catenin signaling and autophagy." (PMID 31799068, 2019). "MEG3 inhibits the invasion of bladder cancer cells by competing with PHLPP2 to bind to miR-27a and negatively regulates c-Myc as a ceRNA." (PMID 32153626, 2019). "For example, ADAMTS9-AS2 is a bladder cancer-related lncRNA4 that interacts with MEG3 in both Ta and T1 networks through sharing four miRNAs (hsa-miR-148b-3p, hsa-miR-143-3p, hsa-miR-574-5p and hsa-miR-4701-3p)." (PMID 31182759, 2019).
bladder cancer (continued). "CARMN (or miR143HG) is another bladder cancer related lncRNA44 that has a strong connection with MEG3 (correlation 0.76) via sharing 5 miRNAs (hsa-miR-148b-3p, hsa-miR-106a-5p, hsa-miR-9-5p, hsa-miR-148a-3p, hsa-miR-501-3p)." (PMID 31182759, 2019). "This study showed that H19, SNHG16, UCA1, PTENP1 and MEG3 were aberrantly expressed in bladder cancer tissues." (PMID 30285771, 2018). "The expression of H19, SNHG16 and UCA1 was significantly elevated in bladder cancer tissues, while PTENP1 and MEG3 were significantly decreased in bladder cancer tissues compared with adjacent normal tissues (P < 0.05)." (PMID 30285771, 2018). "For example, it has been shown that decreased expression of the lncRNA MEG3 results in activation of autophagy in bladder cancer cells." (PMID 26757825, 2016). "It has been shown recently that MEG3 knock down in bladder cancer cells resulted in induction of autophagy, increased cell proliferation and inhibition of apoptosis." (PMID 26757825, 2016). "For example, MEG3 is expressed in many normal tissues, but its expression is lost in primary human pituitary tumors and cell lines as well as in bladder cancer." (PMID 24006935, 2013). "Furthermore, another study MEG3 plays a critical role in bladder cancer by modulating miR-494 and the tumor suppressor gene PTEN." (PMID 40242248, 2025). "Moreover, PTENP1, functioning analogously to MEG3 in bladder cancer, enhances the expression of tumor suppressors like PDCD4 by suppressing miR-20a, thereby inhibiting tumor growth and metastasis." (PMID 40242248, 2025). "In bladder cancer tissues, MEG3 is significantly reduced compared to healthy controls." (PMID 40242248, 2025). "MEG3 serves a crucial role in inhibiting the invasion and metastasis of bladder cancer cells." (PMID 40242248, 2025). "MEG3 expression has been shown to inhibit bladder cancer progression." (PMID 36685879, 2022). "In MEG3 overexpressing bladder cancer, cisplatin could significantly induce cell apoptosis, down-regulate bcl2 expression and up-regulate cleaved-caspase-3 and bax expression." (PMID 31488093, 2019). "Many of the genes in the MEG3 module are cancer-related (more than 80% in T1 and more than 50% in Ta networks), and interestingly in T1 networks, all protein-coding genes detected in the module are bladder cancer-related." (PMID 31182759, 2019). "Our previous studies identified MEG3 as a tumor suppressor gene in bladder cancer." (PMID 31799068, 2019). "An example of a bladder cancer-related mRNA that is found in the MEG3 module is Decorin47." (PMID 31182759, 2019). "However, decreased expression of MEG3 has been reported to activate autophagy in bladder cancer cells." (PMID 26757825, 2016). "In bladder cancer MEG3 activates autophagy, which leads to increased cell proliferation." (PMID 26537449, 2015). "MEG3 was reported to be a novel growth suppressor in human cancer that may play an important role in the development of human pituitary adenomas and bladder cancer cells." (PMID 23977302, 2013). "Moreover, the over-expression of MEG3 markedly suppressed the activation of autophagy and increased apoptosis, whereas knockdown of MEG3 activated autophagy and increased cell proliferation in human bladder cancer cell lines." (PMID 24006935, 2013). "Thus, restoration of MEG3 levels holds therapeutic promise for the treatment of bladder cancer." (PMID 40242248, 2025). "In bladder cancer, while GAS5 suppresses cell proliferation by modulating cellular components like CCL1, it complements MEG3’s actions by also targeting major oncogenic pathways." (PMID 40242248, 2025).
bladder cancer (continued). "In contrast, some lncRNAs (such as lncRNA-RP11-498C9.13, lncRNA MEG3, PCAT29, MIR4435-2HG) have been demonstrated to significantly inhibit the proliferation and invasion of bladder cancer cells by targeting downstream genes." (PMID 39628486, 2024). "MEG3 overexpression has been shown to downregulate miR-96 while upregulating α-tropomyosin 1 (TPM1), which reduced bladder cancer cell viability by increasing apoptotic cell death." (PMID 36685879, 2022). "By sponging miR-494 and miR-374a-5p, MEG3 can up-regulate phosphatase and tensin homolog (PTEN), resulting in cell growth inhibition in bladder cancer and pancreatic ductal adenocarcinoma." (PMID 36551518, 2022). "Numerous studies have confirmed that MEG3 is lowly expressed in various tumors, such as CRC, bladder cancer, and renal cell cancer, and inhibits their migration, invasion, and metastasis." (PMID 33520725, 2020). "Moreover, overexpression of MEG3 inhibits cell invasion and downregulates MMP2 and MMP9 in bladder cancer cells." (PMID 40242248, 2025). "A previous study demonstrated that ADAMTS9-AS2 can regulate MEG3 by acting as a molecular sponge for miR-106a-5p in non-invasive bladder cancer." (PMID 40350996, 2025). "For bladder cancer, three lncRNAs have supporting evidence, and MEG3 and PVT1 have not been verified by the lncRNADisease database." (PMID 35186029, 2022). "For instance, MEG3, a new type of tumor inhibitor, which is downregulated in bladder cancer, was shown to exhibit a negative correlation with autophagy markers (Atg8/LC3)." (PMID 33452730, 2021). "There are some cancer-related genes in the MEG3 module that highly correlate and interact with bladder cancer genes, but no report was found about the activity of these genes in bladder cancer." (PMID 31182759, 2019). "The expression of SNHG16, MALAT1, and UCA1 were up-regulated in bladder cancer tissue, while the expression of YRNA1, YRNA3, YRNA4, YRNA5, and MEG3 were down-regulated." (PMID 29899709, 2018). "Unexpectedly, previous studies have found that low level of MEG3 lncRNA expression correlates with poor survival in multiple cancers and patients with low MEG3 level had shorter recurrence-free survival (RFS) in bladder cancer." (PMID 29870555, 2018). "In addition, a moderate significant correlation of MEG3, SNHG16 and MALAT1 between bladder cancer tissues and paired serum samples was also observed, which provides the strong evidence that BC-related lncRNAs could be released into the circulation and enriched in serum." (PMID 27793008, 2016).
colorectal cancer (44 papers, 2014 to 2025). A primary or metastatic malignant neoplasm that affects the colon or rectum. "MEG3, another classical lncRNAs that has been exhaustively studied in the past two decades,was mostly seen as associated with colorectal cancer across multiple vitamin-related studies." (PMID 38475720, 2024). "Association of maternally expressed gene 3 (MEG3) expression with clinicopathological variables in patients with colorectal cancer (CRC) (n = 80)." (PMID 32219064, 2020). "A Chinese case–control study showed that the MEG3 rs7158663 AA genotype significantly increased colorectal cancer risk compared with the GG genotype." (PMID 33119060, 2020). "The MEG3 rs7158663 AA genotype has significantly increased colorectal cancer risk, as revealed by Cao35." (PMID 28814798, 2017). "We demonstrated, for the first time, that rs7158663 in MEG3 had a strong association with increased risk of colorectal cancer." (PMID 26934323, 2016). "We investigated the association of tagSNPs of MEG3 with colorectal cancer risk in a population of Chinese." (PMID 26934323, 2016). "Notably, a meta-analysis has reported that the MEG3 rs7158663 A/A genotype is associated with an increased risk of gastric and colorectal cancers." (PMID 39529988, 2024). "Therefore, MEG3 holds promise as a viable therapeutic target and diagnostic biomarker for colorectal cancer treatment." (PMID 39830506, 2024). "The objective of the present study was to evaluate whether common single nucleotide polymorphisms (SNPs) in MEG3 could be related with colorectal cancer risk in Chinese." (PMID 26934323, 2016). "To test the hypothesis, we carried out an association study between tagging SNPs (tagSNPs) in MEG3 and colorectal cancer risk in a hospital-based colorectal cancer case-control study comprising 518 patients and 527 control subjects from China." (PMID 26934323, 2016). "However, little is known about the single nucleotide polymorphisms (SNPs) in MEG3 and colorectal cancer risk." (PMID 26934323, 2016). "Moreover, MEG3 overexpression induced cell proliferation and was associated with the development and progression of colorectal cancer." (PMID 26934323, 2016). "The genetic variants of MEG3 may be associated with the expression of MEG3 and consequently influence susceptibility to colorectal cancer." (PMID 26934323, 2016). "Proteins such as MEG3 and SnaR are significantly overexpressed in colorectal cancer and other drug-resistant tumors." (PMID 40191723, 2025). "In colorectal cancer, the MEG3 lncRNA induces ERS, limits tumor cell proliferation, and enhances apoptosis, thereby preventing the malignant transformation of tumor cells." (PMID 40191723, 2025). "There is broad evidence, as reviewed here, from independent groups supporting the role of vitamin D-mediated pathways in the link between MEG3 and colorectal cancer." (PMID 38475720, 2024). "MEG3 acts as a sponge for miR-708, inhibiting the malignant proliferation of colon stem cells in colorectal cancer." (PMID 39830506, 2024). "This upregulation of MEG3 exerts tumor suppressor effects in colorectal cancer by regulating the activity of Clusterin." (PMID 39830506, 2024). "Studies have shown that MEG3 overexpression suppresses the proliferation and metastasis of colorectal cancer cells, but in colorectal cancer tissues and cells, there is a significant downregulation of MEG3 expression." (PMID 39830506, 2024). "To investigate the effect of MEG3 on the development of colorectal cancer, we carried out noctogenesis experiments in nude mice and HE staining assay." (PMID 38309281, 2023). "As a kind of lncRNA, MEG3 has been widely regarded as a tumor suppressor and studied in cancer research, such as squamous cell carcinoma, colorectal cancer, and glioblastoma." (PMID 36778210, 2023).
colorectal cancer (continued). "The effect of MEG3 and miR-31 on the development of colorectal cancer was verified by nude mouse tumor-bearing assay and HE staining." (PMID 38309281, 2023). "The decreased luciferase activity of colorectal cancer cells co-transfected with MEG3 WT and miR-31 confirmed the interaction between MEG3 and miR-31." (PMID 38309281, 2023). "In colorectal cancer, non-small cell lung cancer, thyroid cancer, and acute myeloid leukemia, MEG3 was found to have a high expression in the treatment-sensitive group and to combine the relevant microRNAs to improve therapy sensitivity." (PMID 35592674, 2022). "Meg3 inhibits the development and progression of colorectal cancer by regulating cell proliferation." (PMID 28423647, 2017). "They found that MEG3 predicts a poor prognosis of colorectal cancer by influencing cell proliferation." (PMID 26934323, 2016). "We genotyped six tagSNPs of MEG3 in a colorectal cancer case-control study including 518 cases and 527 control subjects." (PMID 26934323, 2016). "MEG3 exhibits downregulation in colorectal cancer and exerts dual effects on cell behavior." (PMID 39830506, 2024). "The results of dual-luciferase assay showed that MEG3 could specifically inhibit the expression of miR-31, which inhibits the development of colorectal cancer." (PMID 38309281, 2023). "MEG3 can inhibit miR-31, which inhibits the development of colorectal cancer." (PMID 38309281, 2023). "In addition, overexpression of MEG3 attenuates the proliferation and induces apoptosis in different tumor cell lines, such as squamous cell carcinoma and colorectal cancer." (PMID 36778210, 2023). "Another related study showed that pyruvate dehydrogenase E1β subunit (PDHB) may be involved in the occurrence and development of colorectal cancer (CRC) under the regulation of LncRNA maternally expressed gene 3 (MEG3)." (PMID 36335291, 2022). "MEG3 could inhibit the malignant phenotype of many cancers including gastric, breast and colorectal cancers." (PMID 34956908, 2021). "In 2016, an association study including 518 cases and 527 controls was conducted by Cao and colleagues who genotyped 5 tagSNPs in MEG3 and found that rs7158663 AA genotype but not other SNPs increased the risk of colorectal cancer." (PMID 30579356, 2018). "They observed that MEG3 rs7158663, but not other polymorphisms, was associated with colorectal cancer risk." (PMID 29615542, 2018). "We found that MEG3 rs7158663 AA genotype, but not GA genotype, had significant increased colorectal cancer risk, compared with GG genotype (OR = 1.96 and P = 0.006 for AA versus GG, and OR = 1.20 and P = 0.171 for GA versus GG)." (PMID 26934323, 2016). "Interestingly, the MEG3 gene locus has been reported to be hypermethylated in colorectal cancer cells indicating the possible perturbation of MEG3 lncRNA expression in colorectal carcinoma." (PMID 24926662, 2014). "Additionally, miR-708 enhances STAT3 activation by targeting the 3’UTR of SOCS3, and the decreased expression of MEG3 in colorectal cancer (CRC) tissues and cells leads to a reduction in SOCS3 levels, promoting the malignant proliferation of colon stem cells and CRC cell lines." (PMID 39830506, 2024). "Dysregulation of long noncoding RNAs (lncRNAs), such as maternally expressed gene 3 (MEG3) and long intergenic noncoding RNA regulator of reprogramming (linc-ROR), plays a crucial role in colorectal cancer progression." (PMID 39108882, 2024). "Based on these, we inferred that by inhibiting miR-31, a-actin expression, and MMP expression, MEG3 can promote the expression of SFRP1, which in turn inhibits the migration and invasion ability of colorectal cancer cells." (PMID 38309281, 2023). "The cells overexpressing MEG3 exhibited increased ADAR expression, and downregulation of MEG3 was found in colorectal cancer tissues, cell lines and serum." (PMID 33224264, 2020). "MEG3 was found to act as a biomarker and regulate cell functions by targeting ADAR in colorectal cancer." (PMID 33224264, 2020).
colorectal cancer (continued). "Some studies have reported that MEG3 9, lnc-ATB 10 and BLACAT1 11 were up-expressed in colorectal cancer plasma, while NKILA 7 and HOTAIRM1 12 were down-regulated in colorectal cancer tissue." (PMID 32742499, 2020). "The differential expression of MEG3 and linc-ROR between colorectal cancer cells and HeLa cells indicates that the bidirectional CEA promoter exerts a specific regulatory effect on gene expression in colon cancer, establishing it as a promising tumor-specific promoter." (PMID 39108882, 2024). "Interestingly, a significant differential expression of MEG3 and linc-ROR was observed only in colorectal cancer cells." (PMID 39108882, 2024). "MEG3 may exert anti-tumor function in pathogenesis of colorectal cancer by regulating miR-376/PRDK1 signal axis, and MEG3 may become a new target for colorectal cancer treatment." (PMID 35109842, 2022). "Examples include promotion of oesophageal adenocarcinoma cells invasion and metastasis by HNF1A-AS1, control of colorectal cancer cells apoptosis by ZFAS1, reprogramming of induced pluripotent stem cells by RNA-RoR, and regulation of non-small cell lung cancer cells growth and apoptosis by MEG3." (PMID 26848625, 2016). "Furthermore, in a colorectal cancer cell, the anti-apoptotic MCL1 has been reported to be regulated (in vitro) by a number of miRNAs, including miR-876-3p which we predicted to be shared by MEG3 and MCL1." (PMID 24926662, 2014).